YTHDF2 (YTH N6-methyladenosine RNA binding protein F2)
Diseases named in the same sentence as YTHDF2 in open-access papers (continued):
Sharing a sentence is not in itself a finding about the gene and the disease.
acute myeloid leukemia (34 papers, 2020 to 2025). Acute myeloid leukemia (AML) is a group of neoplasms arising from precursor cells committed to the myeloid cell-line differentiation. "The YTHDF2 encoding gene was found to be overexpressed and responsible for development of acute myeloid leukemia (AML), whereas it turned into a tumor suppressor by targeting EGFR, IL11 and SERPINE2 mRNAs for degradation in hepatocellular carcinoma." (PMID 33658012, 2021). "For example, YTHDF2 was increased and functioned as a unique therapeutic target for acute myelocytic leukemia (AML)." (PMID 36870954, 2023). "In the latest study, Zhang et al73 found that YTHDF2 is aberrantly expressed in acute myeloid leukemia patients with oncogenic effects." (PMID 39524539, 2023). "High METTL3, WTAP, FTO, ALKBH5, and YTHDF2 expression has been observed in all subtypes of acute myelogenous leukaemia (AML), and high WTAP, ALKBH5 and IGF2BP1 expression are related to the poor prognosis of AML patients." (PMID 35518355, 2022). "One study has demonstrated that inhibited YTHDF2 selectively compromises acute myeloid leukemia (AML)." (PMID 33692959, 2021). "The mutations of m6A regulatory genes, METTL3, METTL14, YTHDF1, YTHDF2, FTO, and ALKBH5, have been identified in acute lymphoblastic leukemia, multiple myeloma, and acute myeloid leukemia (AML)." (PMID 33898522, 2021). "YTHDF2 was involved the progression of Acute myeloid leukemia (AML) via regulating hematopoietic stem cells (HSCs) activity." (PMID 32814762, 2020). "YTHDF2 promotes the expression of miR-126-3p to promote acute myeloid leukemia progression." (PMID 41184358, 2025). "Additionally, it highlights the potential therapeutic value of targeting YTHDF2/miR-126 for acute myeloid leukemia." (PMID 39524539, 2023). "Moreover, in acute myeloid leukemia, YTHDF2 reduced the half-life of many m6A transcripts that promote the overall integrity of leukemic stem cell function, including tumor necrosis factor receptor Tnfrsf2." (PMID 33726814, 2021). "YTHDF2 alters the stability of mRNAs and ncRNAs containing m6A and has a role in the oncogenesis of acute myeloid leukemia (AML), where its’ overexpression prevents the apoptosis of leukemic stem cells by down-regulating the tumor necrosis factor receptor 2 (TNFR2)." (PMID 33430133, 2021). "Additionally, YTHDF2 is recognized as an oncogene that is upregulated in lung cancer and acute myeloid leukemia (AML) to promote tumor initiation and growth, exhibiting a completely opposite function as in HCC." (PMID 32733807, 2020). "CDK1 inhibitors have great potential in inducing degradation and apoptosis of YTHDF2 in acute myeloid leukemia (AML)." (PMID 40919129, 2025). "Additionally, YTHDF2 is a potential therapeutic target in acute myeloid leukaemia treatment." (PMID 36422864, 2022). "A large number of researches have demonstrated that YTHDF2 plays a crucial role in many physiological functions, including haematopoiesis, stem cell biology, and inflammation, and also regulates the cancer progression, such as acute myeloid leukaemia (AML), and liver cancer." (PMID 35582627, 2022). "In acute myeloid leukemia (AML), YTHDF2 decreases m6A RNA stability and is crucial for AML initiation and propagation." (PMID 34094986, 2021). "For example, YTHDF2 is a critical regulator for acute myeloid leukemia (AML) initiation and propagation." (PMID 33928028, 2021). "YTHDF2 acts as an oncogene that can facilitate cell proliferation and inhibit apoptosis via TNF signaling in acute myeloid leukemia." (PMID 37907575, 2023). "Inactivation of the m6A mRNA reader YTHDF2, which recognizes m6A-modified transcripts to promote m6A-mRNA degradation, results in hematopoietic stem cell (HSC) expansion and compromises acute myeloid leukemia." (PMID 33156926, 2021).
acute myeloid leukemia (continued). "This process results in the establishment of a positive correlation between YTHDF2 and miR-126, as well as a negative correlation between YTHDF2 and downstream target genes of miR-126 in patients with acute myeloid leukemia." (PMID 39524539, 2023). "Besides, findings had uncovered that YTHDF2, an m6A reader, was markedly upregulated in human acute myeloid leukemia (AML), and targeting YTHDF2 might compromise the cancer stem cells in AML." (PMID 35003212, 2021). "In acute myeloid leukemia (AML), YTHDF2 is overexpressed and is required for disease initiation." (PMID 32900991, 2020).
ovarian carcinoma (33 papers, 2020 to 2025). A malignant neoplasm originating from the surface ovarian epithelium. "The abnormal expression of m6A-related regulatory enzymes including METTL3, FTO, ALKBH5, IGF2BP1, YTHDF1, and YTHDF2 is closely linked with the growth, metastasis, invasion, and chemotherapy resistance in ovarian cancer." (PMID 37781028, 2023). "YTHDF1 and YTHDF2 are significantly expressed in ovarian cancer and may be associated with prognosis, while YTHDF3 may increase the pathological staging of ovaries." (PMID 37194218, 2023). "Moreover, YTHDF2 deficiency suppressed the proliferation, anchorage-independent growth, and colony-forming ability of ovarian cancer cell lines." (PMID 35382893, 2022). "Moreover, YTHDF2 was also associated with clinical stage and pathological grade of ovarian cancer, and the higher expression level of YTHDF2 in metastatic OC." (PMID 34794452, 2021). "FBXW7 suppresses tumor development and progression in ovarian cancer by degrading YTHDF2 and enhancing the stability of the pro-apoptotic gene Bcl-2-modifying factor." (PMID 39823500, 2025). "The expression of YTHDF2 is significantly upregulated in epithelial ovarian cancer tissues, and the upregulation of YTHDF2 expression reduces the overall m6A-mRNA levels." (PMID 39062595, 2024). "miR-145 directly targets and downregulates YTHDF2 levels, indirectly upregulating m6A levels, thereby inhibiting the proliferation and migration of epithelial ovarian cancer cells." (PMID 39062595, 2024). "YTHDF2 is highly expressed in human ovarian cancer, and its expression level is positively correlated with the development of ovarian cancer." (PMID 38343637, 2024). "We demonstrated that MEG3 is influenced by METTL3/YTHDF2 methylation and restrains ovarian cancer proliferation and metastasis by binding miR-885-5p to increase VASH1 expression." (PMID 38281945, 2024). "The METTL3/YTHDF2 axis can lead to cisplatin resistance of ovarian cancer by regulating the mRNA stability of IFFO1 in an m6A-dependent manner and inhibiting IFFO1 expression." (PMID 37319315, 2023). "At the post-translational level, FBW7 was shown to be involved in ubiquitin-proteasome degradation of YTHDF2 protein in ovarian cancer." (PMID 37012388, 2023). "For example, F-box and WD repeat domain-containing 7 (FBW7), an E3-ubiquitin ligase, ubiquitinates YTHDF2 and suppresses tumour progression by antagonizing the tumour-promoting effect of YTHDF2 in ovarian cancer." (PMID 36632454, 2023). "We showed that ablation of YTHDF2 significantly prohibits proliferation, colony-forming ability, and anchorage-independent growth of the two ovarian cancer cell lines." (PMID 33658012, 2021). "The wound healing test is used to study the effect of YTHDF2 on the migration of ovarian cancer cells." (PMID 35087835, 2021). "Although YTHDF2 was found to be involved in the development of several cancers, it remains largely elusive if the protein is required for ovarian cancer cell survival and growth." (PMID 33658012, 2021). "The role of YTHDF2 in propelling ovarian cancer development is also verified by the clinical observation that YTHDF2 is upregulated in ovarian cancer samples and negatively associated with prognosis." (PMID 33658012, 2021). "The results showed that the reduction of YTHDF2 led to the weakening of the migration ability of ovarian cancer cells." (PMID 35087835, 2021). "The Kaplan-Meier survival analysis displayed that increased expression of YTHDF2 is significantly correlated with worse overall survival (OS) in ovarian cancer (P = 0.0013), which is in line with the result from the TCGA ovarian cancer cohort." (PMID 33658012, 2021). "In our current study, according to the Kaplan–Meier plotter database, when YTHDF1, YTHDF2, WTAP, FTP, and ALKBH5 were highly expressed in ovarian cancer, they were validated as valuable prognostic risk factors for low OS and PFS with high HR." (PMID 33225598, 2021).
ovarian carcinoma (continued). "To confirm these results, we also evaluated the biological function of ectopic YTHDF2 in ovarian cancer cell lines." (PMID 33658012, 2021). "Here, we have unveiled that the m6A-binding protein YTHDF2 acts as a tumor promoter bolstering ovarian cancer cell propagation and the proteolytic degradation of YTHDF2 induced by FBW7 is required for the tumor inhibitory activity of the latter." (PMID 33658012, 2021). "Collectively, our results clearly demonstrate that FBW7 provokes the expression of pro-apoptotic BMF through an m6A-dependent mechanism by interacting with and degrading the m6A reader YTHDF2 in ovarian cancer." (PMID 33658012, 2021). "Verified that YTHDF2, as an m6A reader, promoted the proliferation and migration of ovarian cancer cells by reducing the overall mRNA level of m6A in ovarian cancer cells, while inhibiting their apoptosis." (PMID 34794452, 2021). "To further explore the relationship between YTHDF2 and cell proliferation and invasion phenotype in ovarian cancer cell lines, we conducted a series experiments in vitro." (PMID 35087835, 2021). "Next, we examined if YTHDF2 orchestrates gene expression in ovarian cancer by conducting an RNA-sequencing analysis." (PMID 33658012, 2021). "We reveal here that overexpression of YTHDF2 prompts ovarian cancer cell propagation by globally modulating mRNA turnover through m6A modification, which is associated with worse overall survival in patients." (PMID 33658012, 2021). "Consistently, YTHDF2 was significantly upregulated in ovarian cancer samples versus normal ovarian tissues in the TCGA database." (PMID 33658012, 2021). "Our study has demonstrated that FBW7 suppresses tumor growth and progression via antagonizing YTHDF2-mediated BMF mRNA decay in ovarian cancer." (PMID 33658012, 2021). "In contrast, Li and colleagues disclosed that YTHDF2 promoted cell proliferation and migration in ovarian cancer." (PMID 34970571, 2021). "The results showed that the expression levels of miR-145 and YTHDF2 had an inverse correlation in ovarian cancer." (PMID 32948220, 2020). "The present study found that the expression levels of miR-145 and YTHDF2 had an inverse correlation in ovarian cancer tissues and cells." (PMID 32948220, 2020). "The results provided a theoretical basis for the application of YTHDF2 and miR-145 in the diagnosis and treatment of ovarian cancer." (PMID 32948220, 2020). "The overexpression of miR-145 inhibited the proliferation, migration, and apoptosis of ovarian cancer cells, which was attenuated by the overexpression of YTHDF2." (PMID 32948220, 2020). "It was novel in revealing the regulatory mechanism of YTHDF2 in ovarian cancer and demonstrating the involvement of miR-145 and YTHDF2 in m6A modification and progression of EOC." (PMID 32948220, 2020). "The CCK8 test results showed that the proliferation of ovarian cancer cells decreased after knocking down YTHDF2." (PMID 32948220, 2020). "The present study reported the mRNA expression of YTHDF2 in ovarian cancer tissues and normal ovarian tissues." (PMID 32948220, 2020). "In summary, this study concluded that YTHDF2, an miR-145-repressed protein, promoted the proliferation and migration of ovarian cancer cells." (PMID 32948220, 2020). "Next, the expression levels of miR-145 and YTHDF2 were found to be inversely correlated in ovarian cancer tissues and cells, and YTHDF2 was the direct target gene of miR-145." (PMID 32948220, 2020). "The present study further analyzed the mRNA expression levels of miR-145 and YTHDF2 in ovarian cancer tissues." (PMID 32948220, 2020). "Next, after the overexpression of YTHDF2, the global mRNA m6A level decreased, the proliferation of ovarian cancer cells increased, cell apoptosis decreased, and migration increased." (PMID 32948220, 2020). "Similar to YTHDF1, YTHDF2 plays an oncogenic role in ovarian cancer." (PMID 40483535, 2025). "Meanwhile, studies have shown that YTHDF2 is significantly upregulated in ovarian cancer tissue." (PMID 38281945, 2024).
ovarian carcinoma (continued). "In addition, data from the TCGA database showed the differential expression of tIGF2BP1, YTHDF1 and YTHDF2 genes between normal and ovarian cancer tissues." (PMID 38714753, 2024). "YTHDF1 and YTHDF2 are considered oncogenes in ovarian cancer." (PMID 36999016, 2023). "Furthermore, FBW7 abrogates the mRNA degradation of YTHDF2 on pro-apoptotic gene BMF by inducing YTHDF2 decay, disrupting ovarian cancer progression." (PMID 36999016, 2023). "In addition, many m6A-related factors such as YTHDF2, LETM1, METL3 and ALKBH5 have also been confirmed to be associated with the malignancy of ovarian cancer." (PMID 37005667, 2023). "However, recent studies showed that YTHDF2 was upregulated in ovarian cancer or triple-negative breast cancer (TNBC)." (PMID 35382893, 2022). "High expression of YTHDF2 in ovarian cancer induces tumor progression." (PMID 36479088, 2022). "By employing a LC-MS/MS assay that allows quantification of m6A level in cells, we showed that ablation of YTHDF2 significantly increases m6A abundance in the ovarian cancer cell lines, OVCAR8 and HEY, which is in accordance with a previous study performed in HeLa cells." (PMID 33658012, 2021). "Also, the flow cytometry analysis indicated that knockdown of YTHDF2 drastically triggers ovarian cancer cell apoptosis." (PMID 33658012, 2021). "Studies have indicated that YTHDF2 promotes the progression of ovarian cancer." (PMID 34794452, 2021). "The m6A consensus sequence identified in SKOV3 cells was GGAC [U/A] that is consistent with previous studies, indicating that YTHDF2 may also bind to m6A in ovarian cancer." (PMID 33658012, 2021). "Importantly and in line with these in vitro results, we also revealed that the expression of BMF is inversely correlated with YTHDF2 expression, whereas is positively associated with FBW7 expression, in ovarian cancer tissues." (PMID 33658012, 2021). "In addition, several other potentially interesting targets of YTHDF2 in ovarian cancer have been identified, such as the putative tumor suppressors TRERF1, ZDHHC14, DIS3L, Vps18, NOD1, and SLC9A8." (PMID 33658012, 2021). "Remarkably, we have provided the first line of evidence demonstrating that YTHDF2 is a tumor promoter in ovarian cancer, because ablation of YTHDF2 dampens cell proliferation and enhances apoptosis, which recapitulates the tumor phenotype in vitro and in vivo caused by FBW7 overexpression." (PMID 33658012, 2021). "In our attempt to identify YTHDF2-targeting mRNAs in ovarian cancer, the RNA-sequencing and m6A-sequencing analyses were conducted, leading to the identification of a number of genes that could be regulated by YTHDF2 in an m6A-dependent manner." (PMID 33658012, 2021). "The expression of YTHDF2 was higher in ovarian cancer tissues than in normal ovarian tissues." (PMID 32948220, 2020). "The results indicated that YTHDF2 promoted ovarian cancer progression." (PMID 32948220, 2020). "In conclusion, YTHDF2, as an important m6A reader, significantly promoted proliferation and migration by decreasing the global mRNA m6A levels in ovarian cancer cells, suggesting the involvement of m6A modification and the reader protein YTHDF2 in the carcinogenesis of EOC." (PMID 32948220, 2020). "The clinicopathological correlation analysis of the DNMT3A level in ovarian cancer showed that the later the clinical stage, the higher the pathological grade, the higher the expression of YTHDF2, and the higher the expression of YTHDF2 in patients with metastasis." (PMID 32948220, 2020). "Moreover, miR-145 can directly target and repress YTHDF2 in ovarian cancer cells." (PMID 40483535, 2025). "Similarly, YTHDF2 mainly acted as an m6A “reader” to degrade mRNA in ovarian cancer cells." (PMID 38281945, 2024). "Moreover, YTHDF2 can be directly targeted and inhibited by miR-145 in ovarian cancer cells." (PMID 36999016, 2023).